NMUR1 (neuromedin U receptor 1)
Diseases named in the same sentence as NMUR1 in open-access papers (continued):
Sharing a sentence is not in itself a finding about the gene and the disease.
tumor (9 papers, 2019 to 2025). "In patients with T1 and T2 tumor sizes, NMUR1 promoter methylation has revealed a significant association with the OR for recurrence (OR = 2.14, 95% CI: 1.08–4.24, P = 0.028)." (PMID 31974445, 2020). "And NMUR1 is expressed on various cell types, including macrophages and endothelial cells, known to be active modulators of the tumor microenvironment." (PMID 39055918, 2024). "In line with previous observations, NMUR1 expression levels in tissue samples were markedly higher in tumor tissues than in adjacent non-tumor tissues." (PMID 39055918, 2024). "The definite molecular mechanisms and exact pathways of how NMUR1 participates in tumor progression and invasion, and immune regulation remain are still required to be investigated in mice model and in vitro experiments." (PMID 39055918, 2024). "Further, multivariate Cox regression analysis identified NMUR1 expression, tumor size, and clinical stage as independent predictors of OS." (PMID 39055918, 2024). "Collectively, our data indicate that NMUR1 is involved in shaping the tumor microenvironment and modulating immune infiltration, establishing it as a promising biomarker for predicting the efficacy of immunotherapy." (PMID 39055918, 2024). "The presented data showed that NMU induces tumour-promoting phenotypes in cancer cells and NMUR1-expressing macrophages, endothelial cells and platelets present in the TME." (PMID 36482448, 2022). "The analysis of gene expression data showed that CRC tissues with relatively high NMUR1 expression are also characterized by increased expression of tumour niche cell markers, including macrophages, endothelial cells and platelets." (PMID 36482448, 2022). "Detection of NMU interaction with cells recruited into the tumour niche shed new light on data obtained from other cancer types where the leading role of NMUR1 was shown." (PMID 36482448, 2022). "CCL20, MMP14, and PCDH7 were upregulated in LUAD tumor tissues and linked to poor clinical outcomes, while BTG2, CD69, GPC3, IL7R, and NMUR1 are the opposite." (PMID 34881236, 2021). "It was found that patients with T1 and T2 tumor sizes and methylated NMUR1 promoters had shorter DFS." (PMID 31974445, 2020). "Therefore, the abnormal NMUR1 expression across pan-cancer in comparison to normal tissues implies its potential role in tumor initiation." (PMID 39055918, 2024). "In conclusion, our investigations provide substantial evidence that NMUR1 may act as a tumor suppressor in CRC." (PMID 39055918, 2024). "To elucidate the mechanisms underlying the poor outcome of CRC with high NMUR1 expression, we decided to identify the types of NMUR1-positive cells present in the tumour tissue, as the tumour composition is not restricted to cancer cells." (PMID 36482448, 2022). "In addition to CRC cells, many other cells present in the tumour microenvironment (TME) express NMUR1; therefore, in addition to its autocrine activity, a paracrine effect of NMU released by CRC cells is expected." (PMID 36482448, 2022). "However, according to published data, NMUR1 is also widely expressed by other cell types present in the tumour niche." (PMID 36482448, 2022). "Considering that the current results regarding NMU receptor signalling do not discriminate between NMUR1 and NMUR2 signal transduction, it is interesting that metastatic tissues express more NMUR1 but pancreatic primary tumours “invest” in NMUR2 overproduction." (PMID 31492042, 2019). "Therefore, the patients with high expression of NMUR1 might present a tumor suppressive TME and benefit more from immunotherapy strategies." (PMID 39055918, 2024). "Therefore, the dysregulated expression and functional impairment of ADCY and NMUR1 could affect the anti-tumor immune reaction of the body’s immune system." (PMID 35627270, 2022). "Thus, we speculated that the high expression of ADCY9 and NMUR1 might facilitate the anti-tumor immunity in the LUAD microenvironment." (PMID 35627270, 2022).
tumor (continued). "Among 135 cases with T1 and T2 tumor sizes, the DFS rates in those with GHSR and NMUR1 methylated genes were compared to the unmethylated group (log-rank test, P = 0.418 and P = 0.031, respectively)." (PMID 31974445, 2020). "Furthermore, through an NMUR1-dependent manner, NMU was found to regulate anti-tumor activity of CD8+ T cells, which are the most powerful effectors in the anticancer immune response and form the backbone of current successful cancer immunotherapies." (PMID 39055918, 2024). "Analysis of total RNA from 46 CRC patient samples using RT-qPCR revealed a significant reduction of NMUR1 mRNA expression in tumor tissues compared to adjacent non-tumor tissues." (PMID 39055918, 2024). "Thus, we expect that none of the analysed cells would secrete a significant amount of NMU into the tumour microenvironment; however, they are potentially able to respond to NMU via NMUR1." (PMID 36482448, 2022). "Interestingly, NMUR1 was also expressed by other cell types potentially present in the TME and known to be active in the tumour niche and on the tumour edges." (PMID 36482448, 2022).
cancer (8 papers, 2015 to 2024). A tumor composed of atypical neoplastic, often pleomorphic cells that invade other tissues. "In this study, we initially discovered an association between NMUR1 expression and the proportion of immune cell infiltration in pan-cancer using TIMER2 and xCELL databases." (PMID 39055918, 2024). "The aggregate data from 33 cancer types in the TCGA dataset compellingly indicated that higher NMUR1 expression is associated with improved OS and DFS." (PMID 39055918, 2024). "Subsequent investigations included a thorough assessment of overall survival (OS) and disease-free survival (DFS) across pan-cancer cohorts to explore the potential of NMUR1 as a prognostic biomarker." (PMID 39055918, 2024). "NMUR1 expression level was also found to be a positive correlation with the different stages and molecular subtypes of certain cancers such as COAD, TGCT, BRCA, and so forth." (PMID 39055918, 2024). "After establishing the expression and survival landscape of NMUR1 in pan-cancer, we explored the immune infiltration of NMUR1." (PMID 39055918, 2024). "We then analyzed the immunotherapy cohorts from pan-cancer to compare NMUR1 with those biomarkers in different ICB treatments." (PMID 39055918, 2024). "In consonance with its expression patterns in most cancers, NMUR1 demonstrated heightened methylation levels in HNSC, BRCA, KIRP, PRAD, COAD, and UCEC." (PMID 39055918, 2024). "This analysis yielded a predictive model for immunotherapeutic response, revealing that NMUR1 expression is modulated by distinct ICB treatments across different cancer models." (PMID 39055918, 2024). "In this study, firstly, we explored the expression level of NMUR1 at pan-cancer level using TCGA and GEO databases." (PMID 39055918, 2024). "Further examination revealed that NMUR1 expression consistently varied with cancer progression, with discernible trends across different pathological stages." (PMID 39055918, 2024). "We conducted a bioinformatics analysis which revealed a huge difference proportion of NMUR1 in different cancers." (PMID 39055918, 2024). "Taken together, these pan-cancer data offered us a perspective that NMUR1 played a crucial role in the initiation and progression of tumors." (PMID 39055918, 2024). "Given the important role of NMUR1 in pan-cancer, we aimed to investigate immune signatures and the function of NMUR1 in CRC cell lines and patient tissues by performing single-cell RNA sequencing and functional experiments." (PMID 39055918, 2024). "Through meticulous analysis involving the ssGSEA algorithm applied to the TCGA-COAD dataset, we deciphered the intricate relationship between NMUR1 expression and various cancer related pathways." (PMID 39055918, 2024). "HPV-positive cancer patients were regarded to be at low-risk, with the exception of patients with both GHSR and NMUR1 methylated." (PMID 31974445, 2020). "NTSR1, NTSR2, GHSR, MLNR, and NMUR1 promoter hypermethylation presented discriminative ROC curve profiles, which clearly differentiate cancer tissues from normal tissues [Area Under Curve (AUC) = 0.6220, 0.5736, 0.8103, 0.6049, and 0.5631, respectively]." (PMID 31974445, 2020). "It has been proven that NMU may be an important resistance-enhancing factor and display an anorexigenic effect in animal models, deeper insight into NMUR1 as a cancer cachexia regulator and drug target would be critical in clinical significance." (PMID 39055918, 2024). "Further, NMUR1 was positively associated with a spectrum of immune cells, notably CD8+ T cells and NK cells, and immune inhibitors such as PDCD1 and CTLA4, across diverse cancers." (PMID 39055918, 2024). "NMU has been shown to play an important role in cancer through NMUR1 or NMUR2 dependent pathway." (PMID 39055918, 2024). "We hypothesized that NMU released by CRC cells influences cancer cells and other NMUR1-positive cells present in the TME, resulting in shorter OS of patients." (PMID 36482448, 2022).
cancer (continued). "Thus, using TCGA database, we analysed the expression of molecular markers of macrophages, endothelial cells and platelets in cancer tissues to identify whether the expression of NMUR1 correlates with these markers." (PMID 36482448, 2022). "However, the role of NMUR1 transferred by PMPs in cancer progression must be further investigated." (PMID 36482448, 2022). "In addition, NMUR2S also co-exists with NMUR2 and/or NMUR1 in many other human cancer cell lines." (PMID 26317338, 2015). "Collectively, these analyses across three independent datasets solidify the concept of NMUR1 as a determinant of immunotherapy response in CRC, enriching our understanding of its role in the immune landscape of cancer therapy." (PMID 39055918, 2024). "Similar to previous research, decreased NMUR1 expression correlated with a poor prognosis in certain cancers, including STAD, COAD, GBM, LGG, and BRCA, as well as in pan-cancer." (PMID 39055918, 2024). "The obtained results showed that NMUR1 expression was frequently elevated in MSI-low and MSS cancers compared with MSI-high cancers." (PMID 36482448, 2022). "NMU binds to the specific receptors NMUR1 or NMUR2, which are unevenly distributed on different types of CRC cells and, as we showed, are related to inducing cancer cell motility." (PMID 36482448, 2022). "The results showed that the downregulation of ADCY9 and NMUR1 in LUAD can inhibit the growth and aggressiveness of cancer, while the upregulation of SYT1 had the contrary effects." (PMID 35627270, 2022). "NMUR1 is expressed by CRC cells, as we reported recently and NMUR1 activity supports cancer cell motility, as receptor silencing decreased the migration of HCT116 cells." (PMID 36482448, 2022). "We confirmed also NMUR1 expression in resting and activated platelets, and interestingly, in platelet microparticles (PMPs) actively engaged in the progression of CRC and other cancer types." (PMID 36482448, 2022). "In line with our hypothesis, NMUR1 was enriched in CD4+ T cells, CD8+ T cells, and macrophage cells across different cancers and positively connected with StromalScores, ImmuneScores, and ESTIMATE scores in pan-cancer." (PMID 39055918, 2024). "Although NMUR1 expression was comparable in patients with or without metastasis, its level was significantly increased in cancers with lymph node invasion and correlated with increased expression of VEGFC (vascular endothelial growth factor C), an inducer of lymphangiogenesis." (PMID 36482448, 2022).
infection (4 papers, 2018 to 2025). The state of being infected such as from the introduction of a foreign agent such as serum, vaccine, antigenic substance or organism. "We next assessed the impact of NMUR-1 loss by comparing proteomes of nmur-1(ok1387) mutants and WT animals during pathogen infection." (PMID 41182048, 2025). "Because of these reasons, we propose that our transcriptomic and proteomic studies are complementary to each other, uncovering different aspects of NMUR-1-mediated host defense against pathogen infection." (PMID 41182048, 2025). "In this study, we examined how NMUR-1 regulates protein expression and host physiology during infection with S. enterica and E. faecalis." (PMID 41182048, 2025). "We focused on two proteins of interest, HSP-60 and ATP-4, both of which were found to be downregulated in nmur-1(ok1387) animals during infection in the proteomic data." (PMID 41182048, 2025). "Utilizing quantitative mass spectrometry, we found that animals with an nmur-1 knockout have a significant decrease in the expression of proteins responsible for ATP biosynthesis during infection." (PMID 41182048, 2025). "Overall, nmur-1(ok1387) animals exhibited significantly reduced expression of proteins involved in transmembrane transport and ATP synthesis during infection with either S. enterica or E. faecalis." (PMID 41182048, 2025). "Genetic or chemical inhibition of F1FO ATP synthase in wild-type (WT) animals mimicked the distinct survival phenotypes of nmur-1 mutants during infection with either pathogen, implicating ATP production as a key downstream effector of NMUR-1-mediated immune specificity." (PMID 41182048, 2025). "Taken together, these results demonstrate that loss of NMUR-1 function reduces ATP concentrations during pathogen infection, which may contribute to the survival phenotypes of nmur-1(ok1387) animals against S. enterica and E. faecalis." (PMID 41182048, 2025). "Here, we used quantitative proteomics and functional analyses to show that NMUR-1 modulates the expression of mitochondrial F1FO ATP synthase subunits and regulates ATP levels during infection, linking neuronal signaling to host energy metabolism." (PMID 41182048, 2025). "Normal human fibroblasts expressing NMU receptor 1 (NMUR1) and treated with NMU-25 peptide show higher viral titer following infection than control cells." (PMID 38921161, 2024). "NFH1 cells expressing an active NMUR1 pathway and treated with 100 nM of NMU-25 peptide showed a significantly higher viral titer three days post-infection compared to cells transfected with the empty vector control plasmid or NMUR1-expressing cells not treated with NMU-25 peptide." (PMID 38921161, 2024). "Notably, infection resulted in increased expression of NMU in wild-type mice, and both NMUR1 KO mice or chimeric mice in which ILC2 do not express NMUR1 were significantly less able to clear N. brasiliensis." (PMID 29593546, 2018).
NMUR1 also shares sentences with these, for which no sentence is quoted: cervical squamous cell carcinoma (1 paper); lymphoma (1); mesothelioma (1); monocytic leukemia (1); osteosarcoma (1); Pheochromocytoma and paraganglioma (1); sarcoma (1).